CYGB (cytoglobin)
Description:
Probable multifunctional globin with a hexacoordinated heme iron required for the catalysis of various reactions depending on redox condition of the cell as well as oxygen availability. Has a nitric oxide dioxygenase (NOD) activity and is most probably involved in cell-mediated and oxygen-dependent nitric oxide consumption. By scavenging this second messenger may regulate several biological processes including endothelium-mediated vasodilation and vascular tone. Under normoxic conditions functions as a nitric oxide dioxygenase (NOD) but under hypoxic conditions the globin may switch its function to that of a nitrite (NO2) reductase (NiR), generating nitric oxide. Could also have peroxidase and superoxide dismutase activities, detoxifying reactive oxygen species and protecting cells against oxidative stress. Also binds dioxygen with low affinity and could function as an oxygen sensor but has probably no function as a respiratory oxygen carrier.
Synonyms: HGb; NOD; STAP
Tractability: Small molecule: a structure with a bound ligand is known; it has a high-quality binding pocket.
Gene: Protein-coding gene on chromosome 17 (76,527,356 to 76,551,175, reverse strand). Ensembl gene ENSG00000161544.
Subcellular location: Cytoplasm; Nucleus
Subcellular location (Human Protein Atlas): Nuclear speckles; Cytosol
Pathways (Reactome):
Metabolism: eNOS activation
Transport of small molecules: Intracellular oxygen transport
Gene Ontology:
Molecular function: carbon monoxide binding; nitric oxide dioxygenase activity, heme protein as donor; nitrite reductase activity; oxygen binding; protein binding; superoxide dismutase activity; heme binding; oxidoreductase activity; oxygen carrier activity; peroxidase activity; antioxidant activity; catalase activity; fatty acid peroxidase activity; iron ion binding
Biological process: nitric oxide catabolic process; removal of superoxide radicals; nitric oxide metabolic process; oxygen transport; response to oxidative stress; fatty acid oxidation; negative regulation of collagen biosynthetic process; negative regulation of fibroblast migration; negative regulation of hepatic stellate cell activation; response to hypoxia
Cellular component: cytoplasm; cytosol; nuclear speck; nucleus
Genetic constraint (gnomAD): Loss-of-function variants: 13 observed, 19.56 expected, observed/expected ratio (o/e) 0.66, 90% interval 0.43 to 1.06. The upper end of that interval is the gene's LOEUF score, 1.06, which puts it in group 4 of 6, group 1 being the genes least tolerant of losing a copy. Missense variants: 218 observed, 245.99 expected, observed/expected ratio (o/e) 0.89, 90% interval 0.79 to 0.99. Synonymous variants: 93 observed, 100.22 expected, observed/expected ratio (o/e) 0.93, 90% interval 0.78 to 1.1.
Homologues: Orthologues: chimpanzee CYGB (100% identical), dog CYGB (96% identical), mouse Cygb (95% identical), guinea pig CYGB (94% identical), rat Cygb (94% identical), macaque CYGB (80% identical), tropical clawed frog cygb (65% identical), zebrafish cygb2 (62% identical), zebrafish cygb1 (45% identical), Drosophila melanogaster glob1 (19% identical), Caenorhabditis elegans glb-14 (15% identical), Caenorhabditis elegans glb-34 (15% identical). Paralogues in human: HBZ (25% identical), HBQ1 (25% identical), HBA1 (24% identical), HBA2 (24% identical), MB (24% identical), HBD (23% identical), HBB (23% identical), HBE1 (22% identical), HBM (21% identical), HBG1 (21% identical), HBG2 (21% identical).
Diseases named in the same sentence as CYGB in open-access papers:
CYGB is named in the same sentence as 70 diseases in open-access papers, as found by Europe PMC text mining. Sharing a sentence is not in itself a finding about the gene and the disease. The quoted sentences say what the papers report.
liver fibrosis (14 papers, 2015 to 2025). "The loss of cytoglobin accelerates liver fibrosis and cancer development despite its etiology in mouse models of chronic liver injury." (PMID 36346805, 2022). "As CYGB was originally identified in rat HSCs, we recently determined its expression and role in liver fibrosis and cancer." (PMID 35504863, 2022). "For instance, FGF2 activates FGFR1 signaling in HSCs and upregulates the level of the CyGB gene to inhibit the transformation of HSCs into myofibroblasts and thereby alleviates liver fibrosis and cirrhosis." (PMID 35951441, 2022). "A study using recombinant adeno-associated virus vector demonstrated that overexpression of cytoglobin prevents free radical-induced HSC activation and liver fibrosis in rats." (PMID 30279328, 2018). "Although the novel hexaco-ordinated globin cytoglobin was identified in activated hepatic stellate cells more than 10 years ago, its role in stellate cell biology and liver fibrosis remains enigmatic." (PMID 26300973, 2015). "Cytoglobin, first named STAP (stellate cell activation-associated protein), was initially located in HSCs (hepatic stellate cells) during their activation upon liver fibrosis." (PMID 26339645, 2015). "Cytoglobin has been reported to exert antifibrotic effects in various liver fibrosis models." (PMID 39316687, 2024). "MF2 cells specifically expressed liver fibrosis-related genes AGTR1, CYGB, PIEZO2, and LPL, and MF5 cells specifically highly expressed immune-related genes TRAC, CD3D, GZMB, and FCGR3A." (PMID 40949143, 2025). "This study demonstrated that AHCC inhibited HSCs activation by inducing cytoglobin through the TLR2-SAPK/JNK pathway and suppressing collagen production via the TLR4-NF-κβ pathway, resulting in the prevention of liver fibrosis progression." (PMID 39316687, 2024). "Cytoglobin (CYGB), a hemeprotein involved in liver fibrosis and cancer development, is expressed in pericytes of all organs." (PMID 35504863, 2022). "However, in the present study, hepatic lipid peroxidation was increased in the Fe-TAA group compared to that in the TAA group, despite the marked suppression of liver fibrosis, suggesting that cytoglobin may be less involved in the suppression of liver fibrosis in this model." (PMID 30279328, 2018). "In this study, we verified whether AHCC intake suppresses the progression of liver fibrosis by the suppression of HSCs activation using a carbon tetrachloride-induced mouse fibrosis model and revealed that AHCC increased the expression of cytoglobin." (PMID 39316687, 2024). "In contrast, the overexpression of CYGB in HSC, either in specific Cygb transgenic mice or through recombinant CYGB injection, hampered the activation of HSC, attenuating lipid peroxidation and oxidative DNA damage in Hep and consequently suppressing liver fibrosis." (PMID 36112670, 2023).
breast cancer (12 papers, 2014 to 2025). A primary or metastatic malignant neoplasm involving the breast. "In this research, a reduction in CYGB expression was observed in tissues linked to ovarian, head and neck, liver, lung, esophageal, pancreatic, and breast cancers." (PMID 39227479, 2024). "In this study, we provide evidence supporting CYGB as a tumor suppressor in breast cancer: CYGB expression was downregulated in breast cancer tissues and cell lines, which was associated with promoter methylation." (PMID 30545372, 2018). "Consistent with literature that CYGB is epigenetically downregulated in several types of malignancies, we detected CYGB down-regulation associated with promoter hypermethylation in breast cancer cell lines and tissues." (PMID 30545372, 2018). "A similar trend of promoter methylation associated with reduced CYGB expression was also detected in breast cancer cell lines." (PMID 30545372, 2018). "CYGB expression was downregulated in breast cancer tissues and cell lines, which was associated with promoter methylation." (PMID 30545372, 2018). "For instance, CYGB exhibits antitumor effects across various human malignancies; however, its expression is often diminished in tissues associated with ovarian cancer, lung cancer, and breast cancer." (PMID 39981244, 2025). "To elucidate the role and underlying mechanism of CYGB in breast cancer, we examined clinical samples and human breast cancer cell lines for CYGB expression and promoter methylation, and assessed the effect of restoration of CYGB expression on proliferation in breast cancer cells." (PMID 30545372, 2018). "In breast cancer, it has been noted that CYGB exhibits low expression attributed to promoter methylation, thereby exerting a tumor-suppressive function." (PMID 39227479, 2024). "In breast cancer, researchers have identified that CYGB inhibits breast cancer by suppressing glucose metabolism." (PMID 39227479, 2024). "Previously, several studies have demonstrated a tumor-suppressive role of CYGB in cancers, especially in breast cancer." (PMID 32908121, 2020). "Ectopic CYGB expression suppressed the malignant properties of breast cancer cells both in vitro and in vivo." (PMID 30545372, 2018). "Taken together, these results suggest that CYGB is a potential tumor suppressor that is suppressed by promoter hypermethylation in breast cancer." (PMID 30545372, 2018). "To further explore the molecular mechanism by which CYGB suppresses breast cancer, we used the proteomics approach of 8-plex isobaric tags for relative and absolute quantitation (iTRAQ) to examine altered pathways in MCF7 cells with stable CYGB transfection." (PMID 30545372, 2018). "The effects and mechanisms of ectopic CYGB expression in breast cancer cells were assessed with molecular biological and cellular approaches in vitro and with a xenograft tumor model in nude mice." (PMID 30545372, 2018). "Demethylation treatment effectively restored CYGB expression, confirming that promoter methylation contributes to suppression of CYGB expression in breast cancer cells." (PMID 30545372, 2018). "The main altered pathways were related to glucose metabolism (metabolic, pyruvate, propanoate, and carbon metabolism, gluconeogenesis and glycolysis pathways), suggesting that CYGB plays a major role in glucose metabolism in breast cancer cells." (PMID 30545372, 2018). "It would be interesting to determine if the CYGB-mediated glucose metabolism regulation pathway can be a valuable potential target for breast cancer prevention and therapy." (PMID 30545372, 2018).
breast cancer (continued). "To investigate the role of CYGB in breast cancer, we first examined its expression in paired tumor and tumor adjacent tissues from 17 patients." (PMID 30545372, 2018). "Further studies are warranted to determine if CYGB-mediated glucose metabolism regulation pathway can be targeted for breast cancer prevention and therapy." (PMID 30545372, 2018). "Our results confirmed that promoter hypermethylation contributes to CYGB suppression in breast cancer and shed lights on the mechanism by which CYGB inhibits breast cancer growth." (PMID 30545372, 2018). "Shivapurkar and co-workers identified three downstream effector genes of CYGB, which were downregulated in CYGB-overexpressing lung and breast cancer cell lines." (PMID 28258342, 2017). "Indeed, the overexpression and/or the induction of CYGB in breast cancer cell lines correlates with the reduction of cell migration and increased cell death." (PMID 34440755, 2021). "The results were validated with The Cancer Genome Atlas (TCGA) dataset with 489 cases, which showed a significant decrease of CYGB expression in breast cancer that includes both invasive ductal breast carcinomas (IDBC) and invasive lobular breast carcinomas (ILBC)." (PMID 30545372, 2018). "The results for the first time suggest that CYGB suppresses breast cancer through inhibiting glucose metabolism, which could be exploited for breast cancer prevention and therapy." (PMID 30545372, 2018). "CYGB is a potential tumor suppressor in breast cancer that is epigenetically suppressed." (PMID 30545372, 2018). "CYGB suppressed the malignant properties in breast cancer cells both in vitro and in vivo." (PMID 30545372, 2018). "Our results shed lights on the mechanism of breast cancer development and suggest that the CYGB-mediated regulation of glucose metabolism could be a target for breast cancer prevention and therapy." (PMID 30545372, 2018). "Thus, our results suggest that CYGB is a potential epigenetically suppressed tumor suppressor gene in breast cancer." (PMID 30545372, 2018). "We investigated the role and mechanism of CYGB in suppressing breast cancer." (PMID 30545372, 2018). "In breast cancer, BRCA1 has been reported as a target of UHRF1-mediated methylation, while in non-small-cell lung cancer, RASSF1, CYGB, and CDH13 have been identified as UHRF1-regulated methylation targets." (PMID 41373864, 2025). "In our previous study, we demonstrated that promoter hypermethylation contributes to cytoglobin (CYGB, the fifth member of globin family) suppression in breast cancer." (PMID 37005662, 2023). "IHC staining of the CYGB-expressing tumors showed lower GLUT1 and HXK2 and higher TIGAR expression, substantiating that CYGB suppresses breast cancer through the regulation of these key glucose metabolism factors." (PMID 30545372, 2018).
breast cancer (continued). "The results were in good accordance with those of quantitative PCR analysis, with CYGB mRNA being abundantly expressed in the G361, p22, and C32TG cell lines but not detected in the A375 and MEWO (melanomas), A549 (lung cancer), and T47D (breast cancer) cell lines." (PMID 24722418, 2014).
head and neck cancer (6 papers, 2006 to 2024). A primary or metastatic malignant neoplasm affecting the head and neck. "The cytoprotective effect of CYGB may cause carcinogenesis or aggressiveness as an oncogene in certain types of tumor including head and neck cancer, which is consistent with our findings." (PMID 28286742, 2017). "In the current study, we measured CYGB gene expression and promoter methylation in a series of head and neck cancer tumours and determined associations with histopathology, clinical characteristics and established markers of tumour hypoxia such as HIF1A expression and tumour thickness." (PMID 19568272, 2009). "Recently presented pilot micro-array data also reveals that CYGB is consistently downregulated in head and neck cancer." (PMID 16449996, 2006). "Furthermore, they also show that targeting cytoglobin and cardiolipins could enhance the therapeutic effectiveness of cisplatin in patients with head and neck cancer, a disease for which chemo-resistance remains a major therapeutic challenge." (PMID 33441751, 2021).
glioma (5 papers, 2012 to 2024). A benign or malignant brain and spinal cord tumor that arises from glial cells (astrocytes, oligodendrocytes, ependymal cells). "In addition, low CYGB expression is found in glioma patients and is associated with higher histological grading and tumor recurrence." (PMID 35504863, 2022). "Moreover, diminished CYGB expression has been reported in individuals with glioma, correlating with elevated histological grade and increased risk of tumor recurrence." (PMID 39227479, 2024). "Furthermore, downregulation of cytoglobin by RNAi has also recently been shown to sensitise glioma cells to oxidative stress, induced by both inhibition of the electron transport chain with antimycin A, and ionizing radiation." (PMID 22359545, 2012). "Interestingly, it has recently been reported that knockdown of cytoglobin expression in glioma cells by RNAi elevates levels of antimycin A-induced hydrogen peroxide." (PMID 22359545, 2012).
lung carcinoma (5 papers, 2006 to 2023). "In most cancers, represented by esophageal and nonsmall-cell lung cancer, CYGB expression is downregulated through promoter hypermethylation." (PMID 36112670, 2023). "In this context, the CYGB mRNA expression has been found downregulated in breast and lung carcinoma tissues with respect to the normal counterpart, and evidence suggested a tumor suppressor role for this globin." (PMID 34440755, 2021). "Promoter methylation of CYGB in lung cancer has recently become the focus of investigation within our research group and may be implicated in ovarian cancer." (PMID 16449996, 2006).
neuroblastoma (5 papers, 2014 to 2024). Neuroblastoma (NB) is the most common solid, extracranial childhood tumor. "A study on recombinant cytoglobin gene transfected into SH-SY5Y neuroblastoma cells using lipofectamine exhibited a neuroprotective effect following cobalt chloride-induced hypoxia." (PMID 29922222, 2018). "Human neuroblastoma cells with overexpressed CYGB showed significant protection from oxidative damage induced by H2O2 or a singlet oxygen generator." (PMID 24722418, 2014). "Indeed, the overexpression of CYGB is detected in some cell lines of neuronal origin (neuroblastomas)." (PMID 24722418, 2014). "In terms of its molecular mechanism of action against neuroblastoma tumors, DpC significantly increased levels of phosphorylated JNK, neuroglobin, cytoglobin, and cleaved caspase 3 and 9, while simultaneously decreasing inhibitory IĸBα levels in vitro." (PMID 27678372, 2016).
non-small cell lung carcinoma (5 papers, 2009 to 2025). A group of at least three distinct histological types of lung cancer, including non-small cell squamous cell carcinoma, adenocarcinoma, and large cell carcinoma. "In particular, co-expression of CYGB and its potential upstream ∆Np63 negatively affected the survival of patients with early-stage non-small cell lung carcinoma." (PMID 35504863, 2022). "In contrast, up-regulation of cytoglobin in other cancers including non-small cell lung carcinoma and cancers derived from the nasal and oral epithelium is also observed indicating a bimodal role of cytoglobin in cancer progression." (PMID 33441751, 2021). "CYGB has been recently suggested to function as a tumor suppressor gene in non-small cell lung cancer and head and neck squamous cell carcinoma." (PMID 24722418, 2014). "Furthermore, CYGB expression has recently been shown by us to be significantly downregulated in 54% sporadic non-small cell lung cancer (NSCLC) in comparison with surrounding ‘normal’ tissues." (PMID 19568272, 2009).